MTOR (mechanistic target of rapamycin kinase)
Diseases named in the same sentence as MTOR in open-access papers (continued):
Sharing a sentence is not in itself a finding about the gene and the disease.
type 2 diabetes (continued). "Type II diabetes mellitus, mTOR (mechanistic target of rapamycin), insulin, cAMP (cyclicadenosine monophosphate) only upregulated at 78 vs. 58 in HN, glycerolipid metabolism, ErbB (erythroblastic oncogene B), arginine and proline metabolism only downregulated at 78 vs. 58 dpc in LW." (PMID 38441676, 2024). "On the other hand, RPS6 was reported to cause metabolic abnormalities in type 2 diabetic patients and may also play a role in reducing focal adhesion through the PI3K-Akt-mTOR signaling pathway." (PMID 38331889, 2024). "Metformin, a biguanide used to treat type 2 diabetes, was found to reduce the risk of dementia, cancer, and other age-related disorders by reducing insulin and IGF-1 levels, inhibiting the mTOR pathway, blocking mitochondrial function, reducing oxidative damage, and activating the AMP kinase." (PMID 39123408, 2024). "Astragaloside alleviated liver injury in type 2 diabetes by promoting AMPK/mTOR-mediated autophagy." (PMID 37810881, 2023). "Moreover, two signaling pathways (mTOR/AMPK) and two disease-associated gene pathways (type 2 diabetes, NAFLD) were identified through the enrichment of DEGs by KEGG." (PMID 37780625, 2023). "Curcumin could attenuate oxidative stress and cardiomyocyte apoptosis to improve the cardiac function in streptozoticin-induced type 2 diabetic rats by the activation of the PI3K/AKT/mTOR pathway in vivo." (PMID 36061427, 2022). "Finally, expression of pathways involved with insulin signaling and type II diabetes mellitus were increased with rapamycin treatment, further confirming the important role of mTOR in regulating glucose metabolism and insulin sensitivity." (PMID 35316218, 2022). "The higher chance of being CVD in patients with type 2 diabetes could possibly be attributed to the increase in plasma BCAA that activate the mammalian target of rapamycin (MTOR) signaling pathway." (PMID 36313094, 2022). "Furthermore, it accomplishes a significant role in the downregulation of the PI3K/AKT/mTOR signaling pathway that is involved in type II diabetes mellitus pathogenesis." (PMID 35337139, 2022). "The results obtained with the use of the queueing theory model confirm earlier reports that mTOR/S6K inhibition could be a therapeutic target in type 2 diabetes." (PMID 36574435, 2022). "Two targets, PRKCA and RHOA proteins, and four signaling pathways, including the mTOR signaling pathway, Type II diabetes mellitus, and Ras and Rap1 signaling pathway, were predicted and considered as key nodes and pathways through which Forsythiaside ameliorated DKD podocytopathy." (PMID 36712665, 2022). "Also, since mTOR is a central regulator of autophagy, we plan to use rapamycin, an inhibitor of mTOR, for the study of the role of autophagy during the evolution of type 2 diabetes in this experimental model." (PMID 34115756, 2021). "Over-nutrition and lack of exercise, also cause chronic mTOR activation, which can account for various age-associated pathologies, such as type II diabetes and cardiovascular diseases." (PMID 34572128, 2021). "We hypothesized that mTOR downstream effectors are metabolic targets in managing type 2 diabetes due to the mTOR central role in glucose and energy metabolism and in the pancreatic progenitors' cell growth." (PMID 32978410, 2020). "Moreover, renal tissue of our type 2 diabetic mouse model exhibited elevated levels of mTOR and S6 phosphorylation by 1.5-fold (p = 0.0145)." (PMID 33303821, 2020). "Importantly, mTOR is a druggable protein and therefore is a potential target for type 2 diabetes interventions." (PMID 32978410, 2020). "Of particular note is the belief that the mTOR signalling pathway provides a means to treat numerous diseased states and this has driven extensive studies investigating how dysfunctional mTOR signalling can lead to cancer, type II diabetes, cardiovascular and neurological diseases." (PMID 30833605, 2019).
type 2 diabetes (continued). "Nevertheless, glucose-dependent suppression of AMPK activity, likely to mimic the effect of Lkb1 deletion on mTOR activity, may provide a means through which changes in glycemia modulate the direction of the effect of TCF7L2 variants on type 2 diabetes risk." (PMID 29967064, 2018). "Moreover, PF-4708671 is used as a tool to study the mTOR pathway in various in vivo and in vitro studies, mainly in models of type 2 diabetes and cancer." (PMID 28068410, 2017). "Differentially methylated genes were enriched in several neuroendocrine signaling pathways including dopamine-DARPP32 feedback (appetite, reward pathways), corticotrophin releasing hormone signaling, nNOS, neuregulin signaling, mTOR signaling, and type II diabetes mellitus signaling." (PMID 28396702, 2017). "For example, several subcategories are related to the regulation of adiposity [“Metabolic Disease” (193 genes), “Endocrine System Disorders” (50 genes), “mTOR Signaling” (31 genes), “Insulin Receptor Signaling” (12 genes), and [“Type 2 Diabetes Signaling” (10 genes)]." (PMID 26445145, 2015). "The nutrient-sensing mTOR (mammalian Target of Rapamycin) pathway regulates cellular metabolism, growth functions, and proliferation and is involved in age-related diseases including cancer, type 2 diabetes, neurodegeneration and cardiovascular disease." (PMID 23117593, 2012). "Therefore, it will be important to investigate further how AldoB overexpression in islets of patients with type 2 diabetes affects beta cell AMPKα/mTOR activities, mitochondrial function, the dynamics of G3BP1+/INS mRNA condensates, and thus insulin production and secretion." (PMID 40355555, 2025). "Given mTOR’s involvement in regulating metabolism, mTOR inhibitors like rapamycin have also been explored for metabolic disorders such as type 2 diabetes and non-alcoholic fatty liver disease (NAFLD), where they may improve insulin sensitivity, lipid metabolism, and reduce inflammation." (PMID 40299431, 2025). "While PTDM shares common risk factors with type 2 diabetes mellitus (T2DM), such as central obesity, age, inflammation, genetic susceptibility, PTDM-specific risk factors including the use of glucocorticoids, calcineurin inhibitors (CNIs) and mTOR inhibitors also play a role." (PMID 40495121, 2025). "In addition, mTOR is dysregulated in many types of cancers and in type-2 diabetes." (PMID 34834120, 2021). "It is well known that aberrant mTOR signaling results in diverse diseases such as diabetes type II, neurological disorders, and cancer, and thus a more complete understanding of the interactions of mTOR and mEAK-7 may be important to preventing or treating these human conditions." (PMID 33364499, 2020). "Additionally, a recent study showed that the protective effects of liraglutide may be associated with increased mTOR expression via activation of the AMPK and PI3K/Akt signaling pathways in rats with type 2 diabetes." (PMID 32082121, 2019). "In addition, a deregulated manner of the IGF-1/Akt/mammalian target of rapamycin (mTOR) participating in exosome secretion could be happened during the onset of type 2 diabetes." (PMID 30127829, 2018). "Metformin, a first-line therapy for type 2 diabetes, has also been investigated in SCI models, where it activates AMPK and inhibits mTOR signaling." (PMID 41181704, 2025). "Metformin, a first-line treatment for type 2 diabetes, activates 5′-AMP-activated protein kinase (AMPK), leading to suppression of the mammalian target of the rapamycin (mTOR) pathway and reduced tumor cell proliferation." (PMID 40243654, 2025). "Metformin, widely used to treat type 2 diabetes, has shown potential nephroprotective effects through activation of AMPK and inhibition of the mTOR pathway." (PMID 41254555, 2025). "C. papaya reinstated the levels of adipocytokines, antioxidant enzymes and mRNA levels of mTOR, TNF-α, IL-1β, IL-6 and IKKβ in the adipose tissues of type 2 diabetic rats." (PMID 36826001, 2023).
type 2 diabetes (continued). "The MAPK, PI3k, AKT, mTOR, and many other common genes/signaling pathways that are involved in disease development mechanisms of both GBM and Diabetes type 2, and they should be investigated for any possible profound relationship." (PMID 35538578, 2022). "Lychee seed extracts significantly improved IR in a type 2 diabetes mouse model by elevating the expression levels of PI3K, AKT, and mTOR to trigger the PI3K/AKT/mTOR signaling pathway." (PMID 34690773, 2021). "Our findings indicate that AMGB has the potential to control TNF-alpha, mTOR, extracellular signal-regulated kinases (ERK), IRS, and PI3K, consequently improving the insulin signaling pathway and preventing type II diabetes mellitus." (PMID 34944525, 2021). "In this sense, metformin (Metf), used in type 2 diabetes mellitus, has become a promising drug in oncology, acting, particularly through inhibition of the AMP-activated protein kinase (AMPK)/mTOR pathway." (PMID 32183017, 2020). "A possible way to prevent the development of therapy resistance against mTOR inhibitors is by combining these drugs with the mitochondrial respiration inhibitor metformin, a drug commonly prescribed for the treatment of type 2 diabetes mellitus (T2DM)." (PMID 28616837, 2018). "Metformin, a first-line oral antidiabetic agent for type 2 diabetes, has been found to play a potential role in anticancer effect through molecular mechanisms of the ATM/LKB1/AMPK axis and mammalian target of rapamycin (mTOR)-signaling pathway." (PMID 24647047, 2014). "In addition, in vivo experiments revealed that VD ameliorated hepatic lipid disorders in type 2 diabetic mice by activating autophagy and regulating AMPK/Akt-mTOR signaling." (PMID 41392241, 2025). "According to our research, obese type 2 diabetic (T2D) rats have been found to have adipose tissue-activated autophagy, which is characterized by increased expression of the autophagy genes Atg5, LC3-II, and Beclin -1 and decreased expression of mTOR." (PMID 38698047, 2024). "Since some lean patients with type 2 diabetes may be more insulin sensitive, PI3K-Akt-mTOR pathway could be further stimulated by insulin and IGF-1, compared to in obese patients." (PMID 35351050, 2022). "Specifically, mTOR acts through S6 kinase to inhibit IRS-1 (insulin receptor substrate), leading to receptor signal resistance, including insulin resistance that contributes to type 2 diabetes." (PMID 34990845, 2022). "Genes involved in translation (EIF2 signalling, mTOR and ‘regulation of eIF4 and P70S6K’ signalling) and stress response (UPR, protein ubiquitination-related pathways) are differentially regulated in β-cells from individuals with type 2 diabetes." (PMID 34944092, 2021). "As far as we know, two previous studies in humans, with small sample size (n = 39–40), examined protein or gene expression of the IGF1, IGF2, IGFBP3, INSR, IGF1R and downstream targets IRS1, IRS2 and mTOR in women with or without type 2 diabetes." (PMID 29486734, 2018). "Administration of the glycolytic inhibitor 2-deoxy-D-glucose (2DG) or the mitochondrial toxin and anti-Type II Diabetes drug, metformin, or AMP mimetic AICAR results in activation of AMPK, repression of the mTOR pathway and prevents maintenance of Late-Phase LTP (L-LTP)." (PMID 20126541, 2010). "In another age-related disease, adult onset diabetes, defective insulin signaling through the insulin-PI3K-Akt pathway, which is upstream of mTOR, is well-established, although inhibition of this same pathway is known to extend lifespan in yeast and C. elegans models." (PMID 20862226, 2010). "Also, in acute stroke patients with type 2 diabetes, metformin could improve the neurological function and oxidative stress status by the AMPK/mTOR signaling pathway and oxidative stress, and in acute ischemic injury, prestroke metformin treatment was neuroprotective involving AMPK reduction." (PMID 34567407, 2021).
type 2 diabetes (continued). "No changes in p-mTOR S2448 and p-ULK1 S757 were found neither in the cortex nor the hippocampus of D-BHB-treated animals as compared to the Coma group." (PMID 33173467, 2020). "It has been previously demonstrated that Metformin, a relatively non-toxic biguanide widely used by millions of type II diabetics around the world, possesses antileukemic activity via, in part, AMPK-mediated antagonism of mTOR/Akt signaling." (PMID 27283492, 2016).
atherosclerosis (203 papers, 2014 to 2026). A disease characterized by the build-up of fatty material and calcium deposition in the arterial wall resulting in partial or complete occlusion of the arterial lumen. "These interventions highlight the potential of targeting mTOR-associated PMs to address the underlying pathology of atherosclerosis." (PMID 40734978, 2025). "Impaired autophagy and mTOR signalling pathways are closely associated with the pathogenesis of atherosclerosis." (PMID 40497340, 2025). "Its activity, however, varies between different cardiovascular conditions, and dysregulation of mTOR signaling is associated with several pathological processes, including atherosclerosis, myocardial infarction, heart failure, and coronary artery disease." (PMID 40734978, 2025). "This review examines the roles of pro-inflammatory and anti-inflammatory T-cells in atherosclerosis, focusing on how their metabolic reprogramming regulates AS progression and the associated molecular mechanisms of mTOR and AMPK signaling pathways." (PMID 39200308, 2024). "Overexpression of MLKL inhibited autophagy flux and activated inflammation in atherosclerosis, which was associated with a mechanistic target of rapamycin (mTOR)-dependent signaling pathway." (PMID 36765043, 2023). "mTOR, chemokine, and T-cell receptor signaling pathways were related to the higher risk of atherosclerosis caused by nilotinib." (PMID 36426222, 2022). "PSAP encodes for prosaposin, which is linked to mTOR signaling and its macrophage expression is reported in atherosclerosis-associated inflammation." (PMID 35860693, 2022). "In summary, DLT activated PI3K/Akt/mTOR-mediated autophagy of vascular adventitial fibroblasts to protect cells from damage caused by atherosclerosis." (PMID 34867337, 2021). "In conclusion, we demonstrated that Danlou tablets provoke the autophagy of vascular adventitial fibroblasts by regulating the PI3K/Akt/mTOR pathway to protect cells from damage caused by atherosclerosis." (PMID 34867337, 2021). "We have previously shown that the mechanistic/mammalian target of rapamycin (mTOR) drives disease progression in mouse models of AD and in models of cognitive impairment associated with atherosclerosis, closely recapitulating vascular cognitive impairment." (PMID 31693798, 2020). "In order to reduce the risk of atherosclerosis, inhibition of mTOR induces autophagy and depletes plaque macrophages." (PMID 30609721, 2019). "Different groups have observed in animal and human models that inhibition of mTOR can result in antiatherosclerotic effects causing prevention or delay of the pathogenesis of atherosclerosis." (PMID 26663990, 2015). "mTOR-mediated signaling pathways, including those regulating oxidative stress and iron homeostasis, can influence the initiation of ferroptosis, which has been implicated in diseases like atherosclerosis and ischemic heart disease." (PMID 40734978, 2025). "Furthermore, mTOR is engaged in cerebrovascular and cognitive dysfunctions associated with atherosclerosis." (PMID 37721413, 2024). "Cholesterol levels in patients on any EVR regimen should however be closely monitored, since dyslipidemia, as a known side effect of mTOR inhibitors, increases the risk of cardiovascular diseases and complications, such as atherosclerosis and myocardial infarction." (PMID 38993848, 2023). "Interestingly, despite the increase in serum lipids, mTOR inhibitors are associated with an overall lower risk of atherosclerosis." (PMID 36211586, 2022). "Deficiency of mTOR, Raptor, or Rictor exacerbated the NO reduction in the Apoe-null mice, illustrating the putative importance of impaired mTOR signaling in the presence of dyslipidemia that promotes atherosclerosis." (PMID 35869262, 2022). "Another cardiovascular topic linked to mTOR function is atherosclerosis." (PMID 30609721, 2019).